STAT3 (signal transducer and activator of transcription 3)
Diseases named in the same sentence as STAT3 in open-access papers (continued):
Sharing a sentence is not in itself a finding about the gene and the disease.
tumor (continued). "In non-small cell lung cancer (NSCLC), aberrant STAT3 activation drives tumor development." (PMID 38339245, 2024). "STAT3 is a marker for tumor angiogenesis which interacts with SRC." (PMID 38257275, 2024). "In addition, IL-22 significantly impaired sorafenib-mediated antitumor effect in HCC by activating tumor cell-intrinsic STAT3/CD155 axis to inhibit the cellular toxicity of sorafenib and NK cell -mediated killing to HCC cells." (PMID 38596684, 2024). "STAT3 is activated in several types of tumor cells and can promote the malignant transformation of cells and inhibit apoptosis, suggesting that the STAT3 signaling pathway could be a new target for tumor gene therapy." (PMID 39411137, 2024). "STAT3 is found to be constitutively active in 90% of human GBM tumours." (PMID 38615034, 2024). "Thus, we surmised that IL-6 was produced directly from the tumor tissue and IL-6 expression was potentiated through the IL-6/STAT3 signaling pathway." (PMID 38389627, 2024). "MiR-21-5p directly targets CCR7, coordinating cancer cell migration, inhibiting its expression, and, therefore, suppressing downstream STAT3, which regulates tumor cell metabolism and NF-κB signaling, mediating neoplasm proliferation, survival, and angiogenesis." (PMID 38542153, 2024). "Additionally, STAT3 signaling in CD4+ T cells promotes regulatory T cell (Treg) accumulation in tumors while inhibiting CD8+ effector T (TEFF)tumor infiltration and antitumor immunity." (PMID 39618825, 2024). "Therefore, we showed much interest in the relationship between tumor cell-intrinsic IL-22/STAT3 axis and NK cell-meditated killing in sorafenib resistance in HCC." (PMID 38596684, 2024). "Both in vitro and in vivo assays demonstrate that neither persistent activation of STAT3 nor its loss confers distinct growth advantages on tumor cells." (PMID 38573819, 2024). "In addition, IL-6 can aggravate tumor invasion through its role in the STAT3-Twist signaling pathway." (PMID 38728503, 2024). "Finally, the knockdown of miR-21 considerably inhibited tumor growth and diminished the expression of STAT3 and hTERT in the xenograft model." (PMID 39201386, 2024). "Notably, in GC mouse models and the tumor epithelium of GC patients, the IL-11-mediated activation of the oncogenic latent transcription factor STAT3 was found to upregulate AIM2 expression." (PMID 39600708, 2024). "GCSF, GCSFR, and STAT3 exhibited increased expression in tumor tissue biopsy samples." (PMID 38538691, 2024). "In mouse xenograft MOLM‐16 tumors, a single intravenous dose of SD‐36 of 25 mg/kg resulted in a significant (>80%, 1 h and >95%, 6 h) and long‐lasting degradation (STAT3 levels below 50% for 4 days after a single administration) of STAT3 protein, culminating in complete tumor regression." (PMID 38845697, 2024). "Notably, SAL similarly reduced the expression level of STAT3/c-Myc pathway-related proteins in mice and effectively inhibited OC tumor growth and glycolysis processes." (PMID 39097833, 2024). "Activates STAT3 signaling to promote tumor and VEGF-A expression and neovascularization." (PMID 39906741, 2024). "In addition, IL-6/JAK/STAT3 signal transduction upregulates immune checkpoint ligand PD-L1 expressed and regulates MDSCs to suppress tumor immunity." (PMID 39372416, 2024). "Moreover, TLR7 ligation can affect the expression of p21 and p-STAT3 to regulate tumor stromal inflammation." (PMID 37803031, 2023). "Thus, an increase in SOCS3 transcription in MBM exposed to factors released from JunBlo microglia cells can inhibit the STAT3-mediated pro-tumor effects." (PMID 37894348, 2023).
tumor (continued). "Microglia stimulate BM cell migration across the endothelium, modulate the expression of specific genes that promote proliferation and impact the levels of ERK (an inhibitor of tumor growth) and STAT3 messenger phosphorylation (a promoter of tumor proliferation)." (PMID 38104104, 2023). "However, our observation that both genetic and pharmacologic inhibition of STAT3 yielded similar results of tumor growth inhibition indicates that the biological effects are direct results of STAT3 inhibition in the tumor." (PMID 37190167, 2023). "Consistently activated STAT3 enhances tumor growth and metastasis." (PMID 37240202, 2023). "Moreover, Western blotting analysis indicated that METTL3 and STAT3 were highly expressed in HCC tissues in comparison with paired non-tumor tissues (n = 10)." (PMID 37231451, 2023). "Moreover, researchers also found that the upregulation of CXCL14 facilitated OC-related tumor cell proliferation through STAT3 signaling pathway, while promoted epithelial-mesenchymal transition and tumor metastasis through Wnt/β-catenin pathway." (PMID 37393391, 2023). "Moreover, other studies demonstrate the activation of cancer stem cells by increasing IL6 and MFG-E8 secretion stemming from overexpression of STAT3 in the tumor microenvironment." (PMID 36662090, 2023). "Luteolin inhibits the STAT3 pathway and PD-L1 expression, which exposes the tumor cells to T cells." (PMID 37958980, 2023). "However, STAT3 has also been attributed tumor suppressor properties as seen in studies with STAT3-deficient mouse models." (PMID 37140667, 2023). "Therefore, STAT3 plays an important role in tumor cell transformation, infiltration, metastasis, and progression." (PMID 37964870, 2023). "In summary, our study demonstrated that activation of IL-6/STAT3/SAA signaling by hepatocyte SGK1 in response to IR promotes the formation of a pre-metastatic niche in the liver of CRC, and that tumor-associated NETs and PMN-MDSCs participate in the formation of CRC in an SGK1-dependent manner." (PMID 36788538, 2023). "Furthermore, this study revealed that it was the increased secretion of IL-23 by MDSCs that subsequently facilitated the epithelial–mesenchymal transition (EMT) of tumor cells to induce chemoresistance of CRC by activating the Stat3-EMT pathway." (PMID 37781363, 2023). "Further, studies have shown that STAT3 may promote tumor growth and hamper the effects of treatment by influencing mitochondrial metabolism or epigenetic regulation or by inducing drug resistance." (PMID 37371647, 2023). "Furthermore, overactivation of STAT3 can promote tumor progression by inducing the polarization of type M2 macrophages and the expression of CD274." (PMID 37724127, 2023). "In addition, inhibition of JAK/STAT3 signaling by compound 11c induced substantial tumor cell apoptosis and influenced cell proliferation." (PMID 37103357, 2023). "Nevertheless, these findings support a vital role of M2 macrophage polarization and a role of IL10 and IL6/STAT3 signaling in HES1 (−) KRAS mutant CRCs that may act in concert to promote tumor progression and metastasis." (PMID 37749297, 2023). "Moreover, it was evident that STK24-mediated regulation of tumor angiogenesis and proliferation was dependent on expression of STAT3." (PMID 36720310, 2023). "Therefore, target genes of HIF-1α such as JMJD1A, VEGF, and STAT3 are activated, and tumor progression is promoted.PHD3 SUMOylation by SUMO2/3 was also found to repress HIF-1-dependent transcriptional activity." (PMID 37415251, 2023). "Furthermore, we demonstrated that both CDK1 and STAT3 were highly expressed in tumor spheres from PANC-1 cells." (PMID 37743465, 2023). "The histoscore of p-STAT3 evaluated by IHC was determined through the combined factors of the intensity and percentage of stained cells within the tumor proportion of the tissue microarray (TMA) cores using an attribute cutoff of 100 for high or low p-STAT3 expression." (PMID 37279067, 2023).
tumor (continued). "Persistent STAT3 signaling activation promotes tumor cell proliferation, survival, and metastasis." (PMID 37686472, 2023). "Elevated CLCF1 and LIF levels may lead to STAT3 activation, which enhances tumor cell proliferation, including HCC." (PMID 37777158, 2023). "CAFs in the tumor microenvironment play an active role in maintaining STAT3 activation in CRC." (PMID 36600243, 2023). "Furthermore, knockdown of STAT3 drastically suppressed xenograft tumor growth of both wild-type and TMEM25 −/− MDA-MB-231 cells in nude mice to a similar level." (PMID 37095176, 2023). "Oral DHA inhibits the development of CAC by inhibiting macrophage-related inflammatory response in the early stage, including reducing the expression of cytokines, down-regulating the phosphorylation of ERK, STAT3 and NF- kB p65, and inhibiting the growth of tumor cells in the late stage." (PMID 38273841, 2023). "Among them, STAT3, a member of the STATs family, has been shown to be involved in macrophage polarization and plays an important role in a variety of inflammatory-immune, fibrotic and neoplastic diseases." (PMID 37081874, 2023). "Subsequent analyses showed that EDX treatment suppressed the expression of STAT3, a transcription factor involved in tumor cell growth, cyclin D1, a cell cycle-related factor, and Ki67, a tumor growth rate marker, which were highly expressed in tumor tissues of Colon26-inoculated mice." (PMID 36751299, 2023). "Similarly, in NSCLC, the lncRNA TNK2-AS1 can also bind to STAT3 to inhibit its degradation, thus activating the STAT3 signaling pathway and promoting tumor progression and angiogenesis." (PMID 37602326, 2023). "STAT3 is generally considered to be an oncogene, although in some particular contexts, it may play a tumor suppressing role." (PMID 37000324, 2023). "Moreover, ectopic silencing of STAT3 by siRNA suppressed these genes and phenotypically resulted in impaired tumor cell proliferation and re-sensitization towards Olaparib." (PMID 37173951, 2023). "Previous studies showed that the MYH9 protein could act as a promoter of tumor stemness that facilitates tumor pathogenesis through the regulation of Wnt-β-catenin-STAT3 signaling, which can further interact with the MET pathway." (PMID 36612298, 2023). "However, in-depth studies focusing on STAT3 expression and the tumor immune microenvironment should be conducted to provide a therapeutic strategy based on the immune system." (PMID 36977736, 2023). "Di (2-ethylhexyl) phthalate (DEHP) might promote the expression of PD-L1 by up-regulating JAK2/STAT3 levels, inhibiting anti-tumor immunity." (PMID 38155974, 2023). "STAT3 is a transcription factor that has a central role in tumor development." (PMID 37372319, 2023). "In addition, interactions between CASC2, miR-18a, PIAS3 (an mRNA molecule), and the STAT3 signaling pathway caused CRC cell multiplication and tumor development." (PMID 38094755, 2023). "In addition, IL-6 secreted by MSCs can promote tumor progression by activating JAK2/STAT3 signaling and upregulating NF-κB." (PMID 37666813, 2023). "However, for the research performed in vivo, they used the STAT3 silencing plasmid enclosed in cationic liposomes to deliver the cargo to the tumor efficiently." (PMID 38067351, 2023). "It has been shown that tumor-associated macrophages (TAMs) can promote CSC phenotypes in mouse models of cancer by acting on the epidermal growth factor receptor (EGFR)/signal transducer and activator of transcription 3 (STAT3)/sex-determining region." (PMID 36675306, 2023). "Current studies have shown that IL-6/JAK/STAT3, in addition to being expressed directly in tumor cells and promoting tumor cell proliferation, differentiation and metastasis, can also appear in macrophages and indirectly affect disease development and progression through macrophage M2 polarization." (PMID 37081874, 2023).
tumor (continued). "Similarly, the IL-9/STAT3 signaling maintains the anti-tumor effect by upregulating FAO activity, decreasing intracellular LPO and resisting ferroptosis in CD8+ Tc9 (cytotoxic T lymphocyte subset 9) cells." (PMID 37700339, 2023). "A close relationship between the STAT3 pathway and tumor autophagy has been established." (PMID 37006252, 2023). "Thus, it was suggested that hyperactivation of STAT3 in myeloid cells simultaneously exerted anti-inflammatory and anti-tumor effects via MCP-2 induction." (PMID 38067195, 2023). "Furthermore, FGFR signaling in breast cancer induces STAT3 activation, which results in a hyaluronic acid-rich microenvironment that contributes to tumor growth and metastasis." (PMID 36966334, 2023). "Interestingly, IL-6 derived from CAFs-induced upregulated phosphorylation of STAT3 in DCs, a surprising result given the previously similar results reported for IL-6 derived from tumor cells." (PMID 38313431, 2023). "The TNF-α targets downregulated by Ent include LIF, a pro-tumorigenic cytokine that triggers tumor STAT3 pathway and contributes to PDAC progression and therapeutic resistance, indicating the potential of HDACi to reduce the pro-tumorigenicity of CAF secretome." (PMID 38057326, 2023). "Furthermore, it was illustrated that STK24 mediated tumor proliferation and angiogenesis in a STAT3-dependent manner using in vivo and in vitro experiments." (PMID 36720310, 2023). "STAT3 is critical in tumor immune evasion and is persistently activated in most malignancies." (PMID 38001876, 2023). "Res is reported to exert its anti-tumor effects mainly by inhibiting STAT3 signaling." (PMID 37298405, 2023). "Importantly, the exclusion of STAT3 or STAT5 signalling inhibits tumour-infiltrating MDSC activation and T cell-dependent neoplastic growth." (PMID 36980527, 2023). "In addition, increased Foxp3 gene expression and Foxp3+ Tregs accumulation were also observed in the regions near the tumor metastasis proximity site, as well as higher STAT3 expression." (PMID 36226375, 2023). "STAT3 also mediates the activation and infiltration of tumor-specific T cells." (PMID 38094755, 2023). "Therefore, we took LGG as an example for immune correlation analysis to further investigate the relationship between STAT3 expression and tumor immunity and the mechanism by which STAT3 affects prognosis of LGG patients." (PMID 37724127, 2023). "In lung adenocarcinoma cells, OSM induces the inhibitory effect of the STAT1-dependent pathway and suppresses the activating effect of STAT3-dependent signaling, which, in combination, suppresses the expression of genes that regulate epithelial-mesenchymal transition and tumor metastasis." (PMID 38022653, 2023). "This may be distinct from the role of IL-6 as a direct driver of STAT3 activation in the tumor microenvironment." (PMID 38022653, 2023). "Furthermore, the in vitro findings in our study underscored that PRMT6’s mediation of tumor metastasis hinged on STAT3 phosphorylation." (PMID 37813837, 2023). "Similarly, by secreting IL-28, MDSCs promote tumor cell STAT3 activation and VEGF upregulation, leading to endothelial cell-induced angiogenesis." (PMID 37465670, 2023). "GBM-initiating cells induce mTOR expression in microglia of mouse models, and the mTOR-mediated signaling of STAT3 and NF-κB contributes to the M2-like microglial phenotype, which hinders infiltration of effector T-cells, tumor proliferation, and immune responses." (PMID 37012233, 2023).
tumor (continued). "To further investigate the photosensitizing mechanism of GTW, we used Western blotting to examine the key proteins involved in NF-κB/IL-6/STAT3 signaling pathway in tumor tissues, including IL-6, NF-κB (p65), phospho-NF-κB (p-p65), STAT3, phospho-STAT3 (p-STAT3)." (PMID 37818040, 2023). "Cyclin D1, which is related to tumor cell proliferation, also decreases with STAT3 inhibition." (PMID 37369757, 2023). "In addition, PD-1 increases FAO and inhibits IFN-γ and glycolysis via STAT3 activation in the tumour-infiltrating CD8+ T-cells." (PMID 37173907, 2023). "Therefore, JAK/STAT3 pathway inhibitors can deter tumor cell growth and stimulate anti-tumor immunity." (PMID 37404473, 2023). "The STAT3 inhibition mediated by curcumin combined with the STAT3 silencing could synergistically suppress tumor growth, which showed better therapeutic efficacy than using single therapy." (PMID 37497002, 2023). "Phosphorylated STAT3 expression in cells that constitute the tumor stroma is now recognized as a critical contributor tocancer pathogenesis and response to therapy pSTAT3 expression and other cell types in the tumor microenvironment." (PMID 37720284, 2023). "Activation of IL-6, TNF and STAT3 signaling is also tumor promoting." (PMID 38035341, 2023). "However, there are studies that demonstrate that suppression of autophagy-related genes in breast cancer stem cells leads to reduced cytokine secretion and suppressed STAT3 signaling pathway, which leads to limitation of tumor growth and progression." (PMID 36833401, 2023). "PIAS3 is upregulated to inactivate STAT3, promoting apoptosis and autophagy in tumor cells." (PMID 37057281, 2023). "In addition to stromal STAT3, high JAK1 and JAK2 expression within the tumour cell cytoplasm was associated with reduced CSS in TNBC cases." (PMID 37199043, 2023). "In contrast, substances that hinder M2 polarization, such as CSF1R inhibitors, corosolic acid, omeprazole, Gpr132 inhibitors, MEK/STAT3 inhibitors, fast-mimicking diets, and antibodies against IL-4, IL-4Rα, and IL-13, are also able to diminish the amount of tumor burden." (PMID 37211559, 2023). "Overactive STAT3 often leads to tumor progression, making it an important target in cancer therapy." (PMID 37887406, 2023). "Moreover, persistent STAT3 activation can promote tumor progression and metastasis in various cancers." (PMID 37465088, 2023). "Additionally, many studies have shown that STAT3 can affect the prognosis of tumor patients by regulating the immune microenvironment (IME) [18−20]." (PMID 37724127, 2023). "In addition, sustained activation of STAT3 maintains self-renewal of tumor stem cells, making tumors prone to recurrence, metastasis, and drug resistance." (PMID 37964870, 2023). "Hypoxia also overexpresses/activates STAT3, leading to tumor progression and drug resistance." (PMID 36703877, 2023). "Similarly, FATP2 can also be overexpressed in PMN-MDSCs, induced by tumor cell-derived GM-CSF and the activation of STAT3 signaling." (PMID 37700339, 2023). "By STAT3 activation, Il-6 introduces expression of genes conducive to tumor progression." (PMID 37373969, 2023). "In contrast, TRPC5, TRPV1, and TRPV2 channels have been found to impede macrophage differentiation, suppress HCC cell proliferation, and ultimately decrease tumor cell invasiveness through the Akt/IκB/NF-κB signaling pathway, STAT3 pathway, and Akt/Nrf2 signaling pathway, respectively." (PMID 37569884, 2023). "Next, we investigated whether Erk1/2/HIF-1α/STAT3/VEGFA is critical for tumor angiogenesis under DOKD feeding." (PMID 37239383, 2023). "Furthermore, STAT3 hyperactivation in immune cells also mediates inhibition of the innate and adaptive immunity of the tumor microenviroment." (PMID 36978108, 2023).